INS (insulin)
Diseases named in the same sentence as INS in open-access papers (continued):
Sharing a sentence is not in itself a finding about the gene and the disease.
Hypertension (continued). "First, in a study on patients with untreated essential hypertension, those with higher pulse pressure (PP) exhibited impaired insulin secretion, increased post-challenge glucose concentrations and greater glucose spikes (PGS) during 75 g oral glucose tolerance testing." (PMID 31462258, 2019). "We previously showed that substitution of the majority of carbohydrate in a high fat diet by purple potatoes (PP) or purple carrots (PC) improved insulin sensitivity and hypertension in an animal model of MetS (obese Zucker rats) compared to a control sucrose-rich diet." (PMID 29642414, 2018). "Fourth, there is evidence that vitamin D may favorably influence stroke outcomes through multiple pathways, including hypertension, insulin resistance and secretion, and chronic inflammation." (PMID 29437901, 2018). "Full-model logistic regression was performed to assess the independent association between vascular outcomes and 1-SD change of each GV index after adjustment for potential confounders including age, sex, body mass index, smoking, hypertension, use of insulin, and HbA1c level." (PMID 29794785, 2018). "Low insulin sensitivity is a well-known independent contributor to high blood pressure in children." (PMID 30035656, 2018). "When comparing the general characteristics according to constitution, participants with the TE type had a higher body weight, BMI, and waist circumference than the other constitutions; thus, high blood pressure, fasting insulin, TGs, and low HDL were confirmed." (PMID 29853979, 2018). "As ARBs are effective antihypertensive and may also improve insulin sensitivity, they seem a good choice to treat hypertension in patients with NAFLD, even if an anti-fibrotic effect is not proven." (PMID 28419124, 2017). "Because many studies reported that; added fructose intake might be related to elevated plasma triglyceride levels, hypertension, increased body weight, increased plasma insulin and glucose levels and hepatic insulin resistance." (PMID 29191195, 2017). "The association between 1L13 and initiation of insulin therapy remained significant after further adjustment for BMI, waist circumference, total cholesterol, HDL, medication for hypertension, smoking, prevalent CVD, lipid lowering medication (HR = 0.49, 95% CI: 0.28, 0.91)." (PMID 28258520, 2017). "Here we investigated whether insulin could inhibit Nrf2 genetranscription, avert Nrf2-stimulation of Agt gene expression via hnRNPF/K, and, subsequently, prevent systemic hypertension and renal injury in T1D mice." (PMID 28324005, 2017). "Lowering uric acid with allopurinol improves insulin sensitivity and hypertension in Pound mice." (PMID 28813453, 2017). "The groups were similar for most characteristics except for higher levels of comorbidities other than hypertension in patients prescribed insulin, and lower levels of prescriptions for statins and aspirin in patients prescribed metformin compared with the other drugs." (PMID 27413012, 2016). "Directly or indirectly through the activity of RAAS, insulin promotes renal tubular to reabsorb Na+ and water, leading to the increased blood volume and cardiac output; this is considered as one of reasons for the development of hypertension." (PMID 27517947, 2016). "The role of FABP4 in the pathogenesis of hypertension might be that FABP4 induces the transformation of the insulin-mediated endothelial nitric oxide synthase (eNOS) pathway, thus reducing NO production and endothelial dysfunction." (PMID 26752184, 2016). "Furthermore, hypertension in insulin-resistant states, including preeclampsia, is determined by inadequate vasodilation and paradoxical vasoconstriction through collateral signaling pathways (VEGF, IGF, and insulin)." (PMID 27738431, 2016). "Finally, there is considerable evidence that resistance to insulin-mediated glucose uptake is increased in patients with essential hypertension when compared to appropriate control groups." (PMID 27001495, 2016).
Hypertension (continued). "Taurine supplementation attenuates hypertension and improves insulin sensitivity in insulin resistant fructose-fed rats, so it may be that high plasma taurine leaves FR male fetuses relatively protected from the effects of fructose." (PMID 26562417, 2015). "In Cameroon, the persisted economic crisis, the insulin-resistance, the resistance of some hypertensions to antihypertensive products and certain germs to synthetic antibiotics has reinforced the recourse to traditional medicine in both urban and rural populations." (PMID 26550547, 2015). "We investigated whether fatty liver disease, as assessed by the fatty liver index, could predict the development of hypertension independently of systemic insulin resistance, inflammatory status and adipokine levels." (PMID 26618774, 2015). "After hypertension model had been fully established, bilateral RDN reversed the elevated systolic blood pressure to normal within 2 weeks, suggesting that RDN could not only prevent hypertension but also reverse the pressor effects of insulin." (PMID 26554798, 2015). "Importantly, long-term exercise alleviates hypertension via improving vascular insulin sensitivity in SHRs." (PMID 25793876, 2015). "In our previous studies, young spontaneously hypertensive rats (ySHRs) with normal blood pressure exhibited significantly decreased aortic vasodilatation to insulin, and exercise mitigates hypertension through improving vascular insulin sensitivity of resistance vessels." (PMID 25793876, 2015). "According to Furukawa and associates, adipocytes produce ROS and the resulting oxidative stress is able to induce insulin resistance in skeletal muscle and adipose tissue and decreased secretion of insulin by pancreatic β cells, thus, generating atherosclerosis and hypertension." (PMID 25759691, 2015). "T2DM patients are often treated with high insulin doses leading to weight gain and high blood pressure and, despite intensified insulin therapy, the treatment goals, which also include improved metabolic control and tight blood pressure control, are not reached." (PMID 26382578, 2015). "After adjusting for age, gender, smoking status, hypertension status, diuretic status, use of insulin or anti-diabetic pills, ACEI, statins, LDL-C, apo A1 and apo B, the OR was 7.01 (95% CI: 3.26 - 15.09) at baseline and 9.10 (95% CI: 3.93 - 21.09) after 6-month follow-up." (PMID 25247018, 2014). "A substantial production of NO has been shown to be induced by inflammation, where inflammatory cytokines such as TNF-α, IL-1β, and interferon-γ stimulate iNOS activity and may be responsible for hypertension and insulin." (PMID 24441717, 2014). "Hypothalamic inflammation, which is induced very rapidly by a high-fat diet may provoke hyperphagia and has been documented to impair insulin release from β cells, peripheral insulin action, and potentiate hypertension." (PMID 24741638, 2014). "And DPN failed to associate with age, diabetic duration, hypertension, insulin treatment, lifestyle intervention, stain medication, current drinking, current smoking, TG, HDLC, HbA1c, eGFR, Matsuda ISI (p > 0.05)." (PMID 25530811, 2014). "Unlike what has been said about HOMA-IR, insulin, and glycemia, the variable that showedthe best diagnostic property for arterial hypertension was WHR, and AUC values close to0.5 were found for WC, BMI, and BF%." (PMID 25119752, 2014). "In summary, the results of this pooled analysis in insulin-naïve patients with T2D show that glycemic control is independent of BMI, but this is not the case for other cardiovascular risk factors, such as hypertension and hypertriglyceridemia." (PMID 25361574, 2014). "Moreover, the NOD Diabetic mice develops hypertension early on and this alteration, like the renal hyperfiltration, can be prevented by insulin administration." (PMID 24400109, 2014).
Hypertension (continued). "These children do have high risk markers for high blood pressure, high cholesterol, high fasting glucose, high CRP and fasting insulin, all factors which cannot be easily measured but could be predicted from fitness tests." (PMID 25074589, 2014). "As 50% of patients with essential hypertension are insulin resistant and hyperinsulinemic, we hypothesized that insulin downregulates the 11beta-HSD2 activity." (PMID 25133511, 2014). "Thus, the present findings provide additional insights about mechanisms and insulin function during high blood pressure development in obese subjects, beyond of those involved in the renal sodium transport." (PMID 24966877, 2014). "Plasma insulin concentrations increase within hours of meal consumption and are greater in both obese animals and humans as well as patients with essential hypertension." (PMID 25520669, 2014). "Despite the size of the support in favour of the insulin hypothesis of hypertension, there is also important evidence against." (PMID 23573411, 2013). "Reaven described “Syndrome X” as consisting of resistance to insulin-stimulated glucose uptake, glucose intolerance, hyperinsulinemia, increased very-low-density lipoprotein triglyceride, and decreased high-density lipoprotein cholesterol and hypertension." (PMID 23896654, 2013). "As shown in this study, selecting females aged between 45 and 65 years, using only premixed insulin, diagnosed with proliferative retinopathy with microalbuminuria, hypertension, and hyperlipidemia, yielded 111 patients, which is enough to conduct any retrospective or prospective studies." (PMID 24025198, 2013). "Progressive loss of metabolic control is evident from a blunting of carbohydrate, fat and protein metabolism, which is commonly manifested through decreased insulin sensitivity, inadequate glucose and lipid control, accompanied by a pro-inflammatory environment and hypertension." (PMID 23822206, 2013). "It has been suggested that engagement in regular physical activity may improve insulin sensitivity, glycemic control, cardiorespiratory fitness and physical function, as well as having favourable effects on hypertension and serum lipid profile." (PMID 23343405, 2013). "Furthermore, a previous study reported that 8 weeks of Ca2+ intake improves insulin sensitivity in essential hypertensive patients." (PMID 23538842, 2013). "The inhibition of insulin-induced NO synthesis in the endothelial cells could result itself in hypertension." (PMID 22448321, 2012). "In addition, insulin-induced sympathetic activity increases the prevalence of hypertension in the metabolic syndrome." (PMID 22845817, 2012). "Hypertension has been shown to induce microvascular changes and these changes may result in a reduced capacity for insulin mediated glucose uptake in the tissue." (PMID 23067205, 2012). "Dermcidin was a potent inhibitor of insulin activated nitric oxide synthase and thereby might play a critical role in the development of hypertension." (PMID 22448321, 2012). "The prevalence of hypertension was higher at higher insulin and HOMA-IR values (P < 0.0001 in each); the odds ratio was 1.6 (95% CI: 1.4–2.0) and 1.6 (95% CI: 1.4–2.0) after controlling for age, sex, BMI, income level, parents' education level, and puberty, respectively." (PMID 22187624, 2011). "Further research will be needed to confirm whether these results generalize to middle-aged, more insulin-sensitive individuals and those with hypertension through a large community-based study." (PMID 21187864, 2010). "Glucose-fed rats displayed higher plasma levels of glucose and insulin, insulin resistance, arterial hypertension, enhanced production of superoxide anion (O2•−) in the heart and aorta and pain polyneuropathy as assessed by the presence of tactile and cold allodynia." (PMID 20830306, 2010).
Hypertension (continued). "Thus, this review highlights and discusses the roles of probiotics on the modulation of lipid profiles, insulin, renin and sexual hormones in the effort to reduce hypertension." (PMID 19865517, 2009). "Hypertension and defects in insulin action may be related to enhanced sympathetic-adrenal medullary (SAM) activity." (PMID 16146570, 2005). "The adrenergic overstimulation that occurs in hypertension also has a humoral origin, since it is triggered by metabolic alterations such as the hyperinsulinemic state and subsequent insulin resistance, as the stimulating effect of insulin has already been documented." (PMID 39457606, 2024). "Normalization of insulin secretion, primarily through dietary correction, as well as pharmacotherapy that restores the functional balance of insulin and renin-angiotensin signaling systems seem essential for the prevention and treatment of IR, hypertension and diabetic complications." (PMID 38323106, 2024). "However, this association was more pronounced in the patients without hypertension and those who were not receiving insulin or other OHAs." (PMID 38170522, 2024). "Interestingly, subgroup analysis and interaction tests indicated that this correlation varied based on smoking status, while it appeared similar across other factors such as gender, age, race, BMI categories, hypertension status, and insulin usage among diabetic patients." (PMID 39850479, 2024). "Third, as we lacked the information on fasting insulin, the risk of incident hypertension with HOMA-IR could not be available for a comparison with the proposed four NI-IR indices." (PMID 38664804, 2024). "In addition, studies have shown that genetic factors, such as high sodium–lithium countertransport, elevated uric acid levels, high fasting plasma insulin concentrations, fat pattern index, and BMI can contribute to the relationship between hypertension and family history." (PMID 39035240, 2023). "The fact that TyG-BMI and TyG-WC are more accurate predictors of MetS and hypertension than TyG index, WC and BMI is of clinical relevance and could be indicated that insulin-related lipid indices may be more accurate for predicting hypertension when taking body fat composition into consideration." (PMID 37273533, 2023). "Hemoglobin, insulin, diuretics, anticoagulation, and β-blockers were associated with higher bilirubin concentrations, whereas the prescription of ASA and ACE inhibitors, hypertension, triglycerides, and HDL cholesterol were associated with a lowering in bilirubin." (PMID 37107322, 2023). "Consumption of LCHF may result in better insulin response and help control hypertension." (PMID 37626767, 2023). "We inferred that the underlying mechanisms of body composition on hypertension risk may be distinct in the presence or different severity of FLD, given that inflammation, insulin resistance, and even the whole body metabolism change when FLD occurs, and these should be explored further." (PMID 38089604, 2023). "Moreover, hypertension, previous heart failure, coronary artery bypass graft, insulin therapy, and older age were independently related to the development of the outcome, while treatment with acetylsalicylic and eGFR were inversely and independently associated with it." (PMID 36769608, 2023). "The use of insulin as opposed to oral therapy may be associated with an increased risk of hypertensive disorders of pregnancy and a higher likelihood of labor induction." (PMID 38063570, 2023). "Our data suggest the importance of insulin dosing in children and adolescents with excess weight and/or high blood pressure and that reducing insulin resistance may be a potentially valuable strategy in lowering high blood pressure in this population." (PMID 36984767, 2023). "Besides hypertension (n = 1) and intrahepatic cholestasis of pregnancy (n = 1) as pregnancy complications, 4 cases suffering from gestational diabetes mellitus (2 of them insulin-dependent) were defined." (PMID 36011745, 2022).
Hypertension (continued). "Adverse intrauterine environmental factors that results in low birth weight may “program” permanent changes in organ development and metabolism (particularly those involved with insulin/glucose metabolism, hypertension and lipid metabolism), leading to future adult disease." (PMID 35402571, 2022). "Indeed, amino acids have been implicated in intracellular signalling, whereby dysregulation of amino acid metabolism may result in inflammation, oxidative stress, and insulin resistance, states involved in the aetiology of hypertension." (PMID 35888725, 2022). "Moreover, RAAS-mediated reactive oxygen species formation not only appears to play a vital role in insulin signaling impairment but also leads to endothelial dysfunction, which contributes to hypertension, atherosclerosis, chronic kidney disease, and cardiovascular disease." (PMID 35448486, 2022). "DOC may inhibit insulin secretion, DOC acetate-induced hypertension was associated with significantly lower levels of plasma insulin in nondiabetic rats." (PMID 35937831, 2022). "Even though insulin/IGF-1 may not play a role in hypertension, insulin/IGF-1 resistance seems to cause hypertension, especially when IGF-1 is associated with excessive NO levels in both vessels and the heart." (PMID 35454166, 2022). "Polynesian ancestry was also nominally associated with WHR (in males), insulin level, triglycerides, hypertension and ischemic heart diseases, but these associations did not remain statistically significant after Bonferroni correction for the multiple traits that we tested in this study." (PMID 33571193, 2021). "Thus, the compensatory hyperinsulinemia required to maintain normoglycemia can aggravate insulin sodium-retaining actions, which may potentially lead to hypertension." (PMID 34966295, 2021). "However, fasting insulin levels, plasma lipid levels, and hypertension risk showed a nonsignificant association with the Thr92Ala polymorphism." (PMID 34660805, 2021). "However, whether the process of aging additively influences insulin- and IGF-1-mediated endothelial dysfunction and antioxidant deficiency in hypertension and its underlying mechanisms remained unclear." (PMID 34203897, 2021). "The obese state may favor a chronic inflammatory condition: adipokines are involved in inflammatory modulation (also attracting macrophages and T-cells), glucose and lipid metabolism, hypertension, or insulin sensitivity, and may also have a role in cancer progression." (PMID 34830209, 2021). "In addition to the type of immunosuppressive medications, other factors, such as the frequency of rejection, infection, insulin resistance, lipid abnormalities, hypertension and other hemodynamic factors, may play a role." (PMID 34640585, 2021). "The ventromedial hypothalamus (VMH) is a key area of integration and exposure to an obesogenic environment during early development may program the VMH of adult offspring to exhibit changes in the sensitivity to leptin and insulin, leading to hypertension and sympatho-excitation." (PMID 34248679, 2021). "Therefore, this study aims to determine the association between insulin secretion (assessed by C-peptide) and arterial stiffness (assessed by brachial-ankle pulse wave velocity (baPWV)) in the Chinese essential hypertensive population without diabetes." (PMID 34976408, 2021). "Therefore, impaired endothelial insulin signaling may be an important link among hypertension, CV, and metabolic diseases." (PMID 32851077, 2020). "Insulin could favor hypertension by acting on insulin resistance." (PMID 32210194, 2020). "Histories of hypertension (86.2%), hyperlipidemia (75.4%), chronic obstructive pulmonary disease (22.3%), peripheral vascular disease (15.5%) and cerebrovascular disease (14.7%) were fairly prevalent, and 81.2% of patients were treated with metformin and 22.2% with insulin at baseline." (PMID 31922023, 2020).